RBM3 (RNA binding motif protein 3)
Diseases named in the same sentence as RBM3 in open-access papers (continued):
Sharing a sentence is not in itself a finding about the gene and the disease.
Barrett esophagus (2 papers, 2014 to 2018). Esophageal lesion lined with columnar metaplastic epithelium which is flat or villiform. "Moreover, RBM3 expression was found to be significantly higher in tumours with associated Barrett’s esophagus or gastric intestinal metaplasia compared to tumours without the presence of these pre-neoplastic lesions." (PMID 24963396, 2014). "RBM3 protein expression was measured by immunohistochemistry using tissue microarrays containing samples from 359 esophageal adenocarcinoma (EAC) and 254 esophageal squamous cell cancer (ESCC) patients with oncological follow-up data." (PMID 30419865, 2018). "In addition, RBM3 expression was analysed in a subset of matched normal squamous epithelium (n = 53), gastric mucosa (n = 117), intestinal metaplasia (IM) (Barrett’s esophagus or gastric IM, n = 72), and lymph node metastases (n = 71)." (PMID 24963396, 2014). "Of note, RBM3 expression was significantly higher in tumours with associated Barrett’s esophagus or intestinal metaplasia compared to tumours without the presence of these pre-neoplastic lesions." (PMID 24963396, 2014).
carcinomas in situ (2 papers, 2012 to 2015). "The putative prognostic role of RBM3 was studied using cystectomy specimens with 152 invasive UCA with 35 matched metastases, 65 carcinomas in situ (CIS), 22 high-grade papillary UCAs (PAP), and 112 benign urothelium cases." (PMID 26577765, 2015).
cardiac arrest (2 papers, 2019 to 2024). Cessation of breathing and/or cardiac function. "With the present study we are the first to our knowledge to observe an upregulation of RBM3 mRNA expression in blood samples of post-cardiac arrest patients treated with TTM." (PMID 31821351, 2019). "In the present study, which is the first to investigate the temperature-dependent regulation of cold-shock proteins in patients after cardiac arrest, we demonstrate that RBM3 mRNA expression is significantly induced by TTM in post-cardiac arrest patients." (PMID 31821351, 2019). "RBM3 mRNA expression was significantly induced in post-cardiac arrest patients in response to TTM." (PMID 31821351, 2019). "RBM3 is a possible biomarker candidate to ensure the efficacy of TTM treatment in post-cardiac arrest patients and its pharmacological induction could be a potential future intervention strategy that warrants further research." (PMID 31821351, 2019). "Our feasibility study demonstrates a translation of the experimental findings to the clinic, thus supporting the concept that RBM3 mRNA expression is temperature regulated in a TTM treated post-cardiac arrest cohort and could possibly contribute to the clinical efficacy of therapeutic hypothermia." (PMID 31821351, 2019). "We recently investigated the gene expression of both cold-shock proteins RNA-binding motif 3 (RBM3) and CIRBP in patients treated with targeted-temperature management (33°C for 24 h) after cardiac arrest." (PMID 38361581, 2024). "This research is a feasibility study aimed to investigate if RBM3 and CIRP are detectable in human blood samples and if their expressions are regulated by TTM during post-cardiac arrest treatment." (PMID 31821351, 2019).
esophageal cancer (2 papers, 2018 to 2025). A primary or metastatic malignant neoplasm involving the esophagus. "In summary, our data show that decreased RBM3 expression is associated with unfavourable esophageal cancer phenotype but is unrelated to prognosis of patients." (PMID 30419865, 2018). "The present study shows that decreased RBM3 expression is linked to a subset of esophageal cancers with unfavourable tumor phenotype." (PMID 30419865, 2018). "In this subset of esophageal cancers, reduced RBM3 expression was statistically linked to adverse tumor features." (PMID 30419865, 2018). "The purpose of this study was to assess the prevalence and clinical significance of altered RBM3 expression in esophageal cancer." (PMID 30419865, 2018). "In summary, the present study shows that decreased RBM3 expression is associated with unfavourable esophageal cancer phenotype, but not significantly linked to patient prognosis." (PMID 30419865, 2018). "However, RBM3 expression was largely unrelated to survival of patients with esophageal cancer (EAC: P = 0.212 and ESCC: P = 0.5992)." (PMID 30419865, 2018). "Therefore, RBM3 cannot be considered as a clinically relevant prognostic biomarker in esophageal cancers." (PMID 30419865, 2018). "The fact that reduced RBM3 expression was linked to development of cancer and was associated with adverse tumor features in our study suggests a tumor suppressive rather than an oncogenic role in esophageal cancers." (PMID 30419865, 2018).
ischemia (2 papers, 2020 to 2025). A hypoperfusion of the BLOOD through an organ or tissue caused by a PATHOLOGIC CONSTRICTION or obstruction of its BLOOD VESSELS, or an absence of BLOOD CIRCULATION. "Translational strategies involve RBM3-mediated therapies to reverse synaptic loss with extended immobility, temperature- or drug-triggered cold-shock protein induction, and metabolic modulators blocking excitotoxic signaling in ischemia or critical illness." (PMID 41154837, 2025). "In hibernating rodents, RBM3 expression is upregulated during torpor, and it allows direct mediation of recovery from ischemia or traumatic injury." (PMID 41154837, 2025). "RBM3-mediated SG formation provides further insight into the pathogenesis of ischemia-reperfusion injury." (PMID 32982696, 2020).
liver cancer (2 papers, 2021). An epithelial or non-epithelial malignant neoplasm that arises from the liver. "Recent studies have shown that eight RNA-binding proteins interact with circRNAs in liver cancer cells, and SCD-circRNA 2 can regulate RNA-binding sequence protein 3 (RBM3) and play an important role in liver cancer." (PMID 32935262, 2021).
metastatic colorectal cancer (2 papers, 2017 to 2022). "The aim of this study was to evaluate RBM3 in metastatic colorectal cancer (mCRC) as a prognostic factor for overall survival and in relation to benefit of first-line chemotherapy." (PMID 28800641, 2017).
metastatic disease (2 papers, 2015 to 2018). "For patients with metastatic disease (n = 88), significant associations were found between RBM3 expression and IGCCC group (p=0." (PMID 25811459, 2015). "In patients with metastatic disease, reduced RBM3 expression correlated significantly with the established prognostic tool (IGCCC), combined tumor marker status and β-HCG level as well as a significantly shorter time to treatment failure." (PMID 25811459, 2015). "Along this line, the observation that the expression of RBM3 was significantly higher in lymph node metastases compared to primary tumors, in particular in PB-type tumors, is highly relevant, as it is the metastatic tumor component that will have the greatest impact on clinical outcome." (PMID 29464064, 2018).
Obesity (2 papers, 2022 to 2024). Accumulation of substantial excess body fat. "Out of multiple proteins altered by obesity with FC > 2, RNA-binding motif protein 3 (RBM3) was increased almost 14-fold." (PMID 38813940, 2024). "Extra-cerebral effects of temperature or FGF21 in the context of obesity could also induce RBM3 release from other organs, and would be the more biologically plausible explanation of the increase in RBM3 in adult patients, thus providing new insight into the obesity paradox." (PMID 35207221, 2022). "Finally, our study did not include any grade III obesity patients, but the trend in our sample suggests that FGF21 and RBM3 would increase accordingly." (PMID 35207221, 2022).
pancreatic adenocarcinoma (2 papers, 2018 to 2022). "This study is, to our best knowledge, the first to report on the expression and prognostic significance of RBM3 in periampullary and pancreatic adenocarcinoma." (PMID 29464064, 2018).
periampullary adenocarcinoma (2 papers, 2018 to 2022). An adenocarcinoma that arises from the periampullary region. "Immunohistochemical expression of RBM3 was analyzed in tissue microarrays with primary tumors and paired lymph node metastases from 175 consecutive patients with resected periampullary adenocarcinoma." (PMID 29464064, 2018). "The aim of the present study was therefore to examine the prognostic and potential predictive significance of immunohistochemical expression of RBM3 in primary tumors and a subset of paired lymph node metastases from a consecutive cohort of patients with periampullary adenocarcinoma." (PMID 29464064, 2018).
testicular cancer (2 papers, 2015 to 2017). A primary or metastatic malignant neoplasm that affects the testis. "Association between clinicopathological characteristics in 206 patients with non-seminomatous testicular cancer and RBM3 expression." (PMID 25811459, 2015).
urothelial carcinoma (2 papers, 2015 to 2022). A malignant neoplasm derived from the transitional epithelium of the urinary tract (urinary bladder, ureter, urethra, or renal pelvis). "RNA-binding motif protein 3 (RBM3), involved in cell survival, has paradoxically been linked to both oncogenesis as well as an increased survival in several cancers, including urothelial carcinoma (UCA)." (PMID 26577765, 2015). "The present study analyzes the putative prognostic role of RBM3 in a large cohort of patients with urothelial carcinoma (UCA) of the bladder by analyzing RBM3 immunohistochemical expression in various benign urothelial tissues, as well as in invasive and metastatic urothelial lesions." (PMID 26577765, 2015). "Thus, while further in-depth research is needed, these findings might provide some clues to the mechanistic basis through which RBM3 sensitizes cells to chemotherapy in urothelial carcinoma." (PMID 35109796, 2022). "Based on their results, the authors postulated that RBM3 expression may be used as a marker of disease progression and that IHC assessment of RBM3 expression could become a valuable tool to more accurately predict aggressiveness of urothelial carcinoma." (PMID 26577765, 2015).
viral infection (2 papers, 2014 to 2016). "More details remain to be determined for RBM3-mediated viral infection and a potential relation to immune response." (PMID 27147467, 2016). "As RBM3 is involved in a variety of transcriptional and translational events, it is not surprising that it also exerts functions in viral infection." (PMID 27147467, 2016).
asthma (1 paper, 2022). "Rbm3−/− and Rbm3−/−Rag2−/− mice exposed to asthma-associated Alternaria allergen develop enhanced eosinophilic lung inflammation and ILC activation." (PMID 35908044, 2022). "We next performed in vivo asthma model experiments with Rbm3−/− mice to assess lung inflammatory and ILC responses." (PMID 35908044, 2022). "Since we were interested in RBP function using in vivo asthma models, we focused on regulation by RBM3 given that Rbm3−/− mice are viable and not known to spontaneously have immune disease." (PMID 35908044, 2022).
clear cell carcinoma (1 paper, 2025). "High RBM3 expression was most frequently observed in mucinous carcinoma (88.2%), followed by clear cell carcinoma (71.9%), endometrioid carcinoma (69.0%), and serous carcinoma (34.3%)." (PMID 40506997, 2025). "Representative images of the RBM3 expression intensity (negative to strong) in serous and clear cell carcinoma are shown." (PMID 40506997, 2025).
cognitive deficits (1 paper, 2020). "Therefore, we considered whether HT to attenuate TBI‐induced cognitive deficits and AD‐like tau phosphorylation is also mediated by RBM3 in this study." (PMID 32648620, 2020).
colorectal tumors (1 paper, 2022). "RBM3, a translation-regulating protein, is significantly up-regulated in human tumors, showing stage-dependent increases in colorectal tumors." (PMID 35328637, 2022).
cryptorchidism (1 paper, 2016). The failure of one or both testes of a male fetus to descend from the abdomen into the scrotum during the late part of pregnancy. "Expression of CIRP and RBM3 decreases under experimental heat stress or cryptorchidism, with a more rapid response of CIRP (6 h) to hypothermia than RBM3 (12 h)." (PMID 27147467, 2016).
diabetes (1 paper, 2014). "The two other genes, Rbm3 and Stng2, have not been associated previously with diabetes or β cell." (PMID 25347859, 2014). "We have not pursued studies in the Rbm3 and Stng2 genes because they were not suspected to play a role in β‐cell physiology or diabetes based on their expression pattern and the review of the available literature." (PMID 25347859, 2014).
diabetic retinopathy (1 paper, 2025). "Single-cell mRNA sequencing of retinal cells demonstrated that Cirbp, Mt1, Rbm3, Hmgb2, Mt2 are upregulated in mice with diabetic retinopathy in all retinal cells analyzed (rods, cones, Muller ̈ cells, retinal glia)." (PMID 40979707, 2025).
endometriosis (1 paper, 2025). The growth of functional endometrial tissue in anatomic sites outside the uterine body. "This study employed an integrated multi-omics approach to identify and validate five core molecules (SRPRB, RBM3, INSIG2, GYG1, and FBXW2) demonstrating significant differential expression in both endometriosis and RIF, with robust diagnostic discriminatory power." (PMID 41462508, 2025). "Western blot analysis consistently demonstrated that the protein expression levels of SRPRB, RBM3, INSIG2, GYG1, and FBXW2 were significantly reduced in both endometriosis and RIF groups compared to the normal group, with statistical analysis validating these findings." (PMID 41462508, 2025).
eosinophilia (1 paper, 2022). "As expected, there was an increase in lung ILC type 2 cytokine and IL-17a production and eosinophilia in Rbm3−/− mice compared to WT mice." (PMID 35908044, 2022). "BAL and lung eosinophilia were also significantly increased in Rbm3−/− mice." (PMID 35908044, 2022). "Thus, RBM3 directly suppresses lung ILC activation by IL-33 in vitro and in vivo, and this leads to significant differences in eosinophilia and neutrophilia in vivo." (PMID 35908044, 2022).
germ cell tumours (1 paper, 2015). "Taken together, our findings suggest that RBM3 may be a potential biomarker for treatment stratification in patients with metastatic non-seminomatous germ cell tumours, and therefore merit further validation." (PMID 25811459, 2015).
Hepatic steatosis (1 paper, 2021). Steatosis is a term used to denote lipid accumulation within hepatocytes. "Expression of Rbm3 and Gadd45b and their potential impacts on liver metabolism could be a consequence and/or a cause of the reduced adiposity and hepatic steatosis of the Csf1rko." (PMID 34081701, 2021).
injury (1 paper, 2019). Damage inflicted on the body as the direct or indirect result of an external force, with or without disruption of structural continuity. "Our findings indicate RBM3 as a potential target to maintain the proliferation capacity of NSCs under hypoxia, which can be important in NSC-based therapies of acute brain injury and chronic neurodegenerative diseases." (PMID 31824945, 2019).
invasive breast carcinoma (1 paper, 2021). A carcinoma that infiltrates the breast parenchyma. "In addition, in invasive breast cancer, high RBM3 expression was found to act as a favorable prognostic indicator with prolonged survival and showed a significant correlation with less aggressive phenotypes." (PMID 34398362, 2021).
invasive carcinoma (1 paper, 2011). A carcinoma that is not confined to the epithelium, and has spread to the surrounding stroma. "While absent or weakly expressed in benign prostatic glands, RBM3 was clearly up-regulated in prostatic intraepithelial neoplasia (PIN) and in invasive carcinoma RBM3 was expressed in various fractions and intensities with 33 (37.5%) cases lacking RBM3 expression." (PMID 21955582, 2011).
Lewy body dementia (1 paper, 2024). A progressive form of dementia characterized by the presence of protein deposits called Lewy bodies in the midbrain and cerebral cortex, and loss of cholinergic and dopaminergic neurons. "In addition, the downregulation of RBM3 has been documented to induce synaptic loss, leading to neurodegeneration and thus representing a promising therapeutic target for Lewy body dementia (LBD)." (PMID 39507532, 2024).
lung adenocarcinoma (1 paper, 2020). A carcinoma that arises from the lung and is characterized by the presence of malignant glandular epithelial cells. "The results from this study support that high protein expression of RBM3 is linked to improved outcome in lung adenocarcinoma." (PMID 32491279, 2020).
mood disorder (1 paper, 2023). A cognitive disorder a disturbance in which the person's mood is hypothesized to be the main underlying feature. "To understand the association between Tcore and mood disorders we used the chronic social defeat stress (CSDS) paradigm to investigate the effects of chronic stress on Tcore and expression of Cirbp, Rbm3 and Hsf1." (PMID 37463657, 2023). "Patients with mood disorders exhibit a higher expression of Rbm3 compared to healthy controls." (PMID 37463657, 2023).
myotonic dystrophy type 1 (1 paper, 2018). Steinert disease, also known as myotonic dystrophy type 1, is a muscle disease characterized by myotonia and by multiorgan damage that combines various degrees of muscle weakness, arrhythmia and/or cardiac conduction disorders, cataract, endocrine damage, sleep disorders and baldness. "Metformin was proposed to act as a modifier of alternative mRNA splicing of a subset of genes mis-splicing in myotonic dystrophy type 1 by activation of AMPK and downregulation of the expression of the RNA-binding protein 3 (RBM3)." (PMID 29473878, 2018).
nasopharyngeal carcinoma (1 paper, 2023). A carcinoma arising from the nasopharyngeal epithelium. "For instance, lncRNA DANCR binds to RNA-binding protein 3 (RBM3) to stabilize SOX2 mRNA, then regulating cell proliferation in nasopharyngeal carcinoma." (PMID 36973749, 2023).
Neurodegeneration (1 paper, 2020). Progressive loss of neural cells and tissue. "RBM3 may be a potential target for neurodegeneration diseases." (PMID 32648620, 2020).
non-alcoholic fatty liver disease (1 paper, 2019). "Indeed, dysregulation of RAVER1 and RBM3 has been recently related with the development of non-alcoholic fatty liver disease, while RAVER1 has been found to be dysregulated in patients with cardiovascular disease at higher risk of type-2 diabetes development." (PMID 31561558, 2019).
oesophageal cancer (1 paper, 2018). "The data from this study show, that altered RBM3 expression – a strong prognostic feature in several cancer types – is statistically linked to adverse tumor features in oesophageal cancer but does not have an obvious impact on clinical outcome." (PMID 30419865, 2018). "In summary, the present study shows that decreased RBM3 expression is associated with unfavourable oesophageal cancer phenotype, but does not predict patients’ prognosis." (PMID 30419865, 2018).
Parkinson disease (1 paper, 2025). A progressive degenerative disorder of the central nervous system characterized by loss of dopamine producing neurons in the substantia nigra and the presence of Lewy bodies in the substantia nigra and locus coeruleus. "In different Parkinson disease (PD) models, a reduction of apoptosis has also been observed after overexpression of RBM3 in SH-SY5Y cells." (PMID 40124786, 2025).